PFKM (phosphofructokinase, muscle)
Description:
Catalyzes the phosphorylation of D-fructose 6-phosphate to fructose 1,6-bisphosphate by ATP, the first committing step of glycolysis.
Synonyms: ATP-PFK; PFK-A; PFKX; PFK-1; PPP1R122; GSD7; PFK1; PFKA
Tractability: PROTAC: ubiquitination databases record sites on it; its protein half-life has been measured.
Target class: Enzyme
Gene: Protein-coding gene on chromosome 12 (48,105,139 to 48,150,704, forward strand). Ensembl gene ENSG00000152556.
Subcellular location: Cytoplasm
Subcellular location (Human Protein Atlas): Endoplasmic reticulum; Principal piece
Pathways (Reactome):
Metabolism: Glycolysis
Gene Ontology:
Molecular function: 6-phosphofructokinase activity; ATP binding; fructose binding; identical protein binding; kinase binding; protein binding; fructose-6-phosphate binding; phosphofructokinase activity
Biological process: fructose 6-phosphate metabolic process; glycolytic process; glycolytic process through fructose-6-phosphate; muscle cell cellular homeostasis; positive regulation of transcription by RNA polymerase II; canonical glycolysis; fructose 1,6-bisphosphate metabolic process
Cellular component: 6-phosphofructokinase complex; apical plasma membrane; nucleus; cytosol; membrane; cytoplasm; sperm principal piece
Genetic constraint (gnomAD): Loss-of-function variants: 49 observed, 80.31 expected, observed/expected ratio (o/e) 0.61, 90% interval 0.48 to 0.77. The upper end of that interval is the gene's LOEUF score, 0.77, which puts it in group 3 of 6, group 1 being the genes least tolerant of losing a copy. Missense variants: 631 observed, 980.62 expected, observed/expected ratio (o/e) 0.64, 90% interval 0.6 to 0.69. Synonymous variants: 318 observed, 351.03 expected, observed/expected ratio (o/e) 0.91, 90% interval 0.83 to 0.99.
Homologues: Orthologues: chimpanzee PFKM (100% identical), macaque PFKM (99% identical), mouse Pfkm (98% identical), guinea pig PFKM (98% identical), rat Pfkm (98% identical), dog PFKM (97% identical), rabbit PFKM (97% identical), pig PFKM (96% identical), tropical clawed frog pfkm (83% identical), zebrafish pfkma (78% identical), zebrafish pfkmb (78% identical), Drosophila melanogaster Pfk (60% identical), and 1 more. Paralogues in human: PFKP (71% identical), PFKL (69% identical).
Diseases named in the same sentence as PFKM in open-access papers:
PFKM is named in the same sentence as 95 diseases in open-access papers, as found by Europe PMC text mining. Sharing a sentence is not in itself a finding about the gene and the disease. The quoted sentences say what the papers report.
breast carcinoma (36 papers, 2013 to 2026). "PFKM genetic mutation associated with different cancers, including human melanomas, breast cancer, bladder cancer, non-small-cell lung cancer, and glioma has also been observed." (PMID 35328104, 2022). "PFKM, the second rate-limiting enzyme in the glycolysis pathway, has been shown to be closely related to the increased risk of breast cancer." (PMID 35223866, 2021). "Looking at the biological functions of CCNE2, HPSE, and PFKM proteins, they are for the most part, involved in cell cycle G1/S transition, proliferation and carcinogenesis, and associated with breast cancer." (PMID 28505145, 2017). "The current study was designed to assess the expression level of three key glycolytic genes, HK2, PFKM, and PKM2, along with their association with clinicopathological parameters and molecular subtypes in breast cancer cohort of Pakistan." (PMID 35328104, 2022). "A genome-wide association study and an in silico study analyzed the role of the PFKM as a novel breast cancer gene and as a potential therapeutic target for glycolysis, respectively." (PMID 35328104, 2022). "Taken together, all these findings are indicative of the role of HK2, PKM2, and PFKM genes in tumor growth, proliferation, lympho-vascular invasion, and metastasis in breast cancer." (PMID 35328104, 2022). "HK2 and PKM2 were found to be upregulated in luminal B, whereas PFKM was overexpressed in the luminal A subtype of breast cancer." (PMID 35328104, 2022). "Our investigation also revealed that other isoforms of phosphofructokinase, i.e., PFKL and PFKM, do not play important roles in promoting breast cancer progression as only high PFKP gene expression is associated with poor survival in breast cancer patients." (PMID 29069720, 2017). "In the present study, the expression profiles of key metabolic genes (HK2, PFKM, and PKM2) were assessed in the breast cancer cohort of Pakistan using quantitative polymerase chain reaction (qPCR) and IHC." (PMID 35328104, 2022). "Among molecular subtypes of breast cancer, luminal B subtype patients showed a significant increase in HK2 and PKM2 expression, whereas most samples with upregulated PFKM fell into the luminal A subtype." (PMID 35328104, 2022). "Muscular phosphofructokinase (PFKM), a member of the phosphofructokinase (PFK) family, can promote the growth of muscle-infiltrating bladder cancer and can be used as a new breast cancer gene, and its expression level can distinguish normal tissues from CC tissues." (PMID 33228592, 2020).
hepatocellular carcinoma (9 papers, 2010 to 2025). A malignant tumor that arises from hepatocytes. "In ovarian cancer and hepatocellular carcinoma, PFKM expression is positively correlated with poor survival and progression." (PMID 41184232, 2025). "PFKM can induce glycolysis in hepatocellular carcinoma cells, whereas inhibition of PFKM can dampen glycolysis in macrophages, affecting macrophage functions and tumor development." (PMID 38331868, 2024). "During hepatocellular carcinoma, ZEB1 has been shown to enhance the Warburg effect, facilitating tumorigenesis and metastasis by transcriptionally activating PFKM." (PMID 39684755, 2024). "In hepatocellular carcinoma (HCC), METTL3 expression positively correlated with glycolysis genes SLC2A1, HK2, PFKM and PKM." (PMID 33669361, 2021).
colorectal cancer (8 papers, 2020 to 2025). A primary or metastatic malignant neoplasm that affects the colon or rectum. "Further experiments revealed that silencing CDKN2A markedly decreased the mRNA levels of the phosphofructokinase genes PFKL and PFKM in colorectal cancer cell lines." (PMID 38888512, 2024).
cardiac hypertrophy (7 papers, 2009 to 2024). "Mice deficient in PFKM (Pfkm−/−) had high lethality around weaning, reduced lifespan, exercise intolerance and had progressive cardiac hypertrophy with age because of metabolic alterations." (PMID 37894945, 2023). "Two-month-old PFKM knockout mice developed cardiac hypertrophy and evident cardiomegaly with age12." (PMID 35804014, 2022).
glioblastoma (7 papers, 2017 to 2026). The most malignant astrocytic tumor (WHO grade IV). "Here we show, using an orthotopic xenograft glioma mouse model, that PFKM is deubiquitinated and translocated into nucleus upon glucose deficiency, thereby activating fatty acid oxidation (FAO), which sustains tumor cell survival and ultimately promotes glioblastoma (GBM) development." (PMID 41818193, 2026).
Tarui disease (7 papers, 2016 to 2025). "Mutations in muscle-type phosphofructokinase (PFKM) have been shown to cause glycogen storage disease VII (Tarui disease)." (PMID 36187097, 2022). "Glycogen Storage Disease Type VII (GSD VII) stands out as an exceedingly rare autosomal recessive glycogen storage disorder resulting from homozygous or compound heterozygous mutations in the PFKM gene, responsible for encoding the muscle phosphofructokinase (PFK) enzyme." (PMID 39156960, 2024). "In Tarui disease, reduced enzyme activity of muscle phosphofructokinase (PFKM) is detected resulting in impaired phosphorylation of fructose 6-phosphate to fructose 1,6-bisphosphate." (PMID 27303362, 2016). "In our patients with Tarui disease, a slight residual PFKM activity of 3–4% out of normal was found in enzyme activity analyses, which might lead to a slight increase of lactate during exercise." (PMID 27303362, 2016).
diabetes (6 papers, 2014 to 2022). "The differential expression of PFKM, GAPDH, ACO2, and MDH2 in the urinary exosomes of diabetic patients can serve as potential biomarkers for diabetes monitoring, providing a promising method for noninvasive diabetes diagnosis." (PMID 36187097, 2022). "The molecular understanding of PFK isoform selectivity, coupled with future studies of the pyrazolo-oxazepine scaffold, could open the door to selective activation of PFKM and PFKP, and the development of new pharmacological therapies for diabetes and cancer." (PMID 34320407, 2021). "In diabetic patients, aerobic oxidative metabolism is reduced, and the expression of aerobic oxidative metabolism-related proteins PFKM, GAPDH, ACO2, and MDH2 in urinary exosomes is reduced, which may become potential biomarkers for monitoring changes in diabetes." (PMID 36187097, 2022).
glycogen storage disease (6 papers, 2009 to 2024). "Glycogen Storage Disease Type VII (GSD VII) is a rare glycogen metabolism disorder resulting from mutations in the PFKM gene, inherited in an autosomal recessive manner." (PMID 39156960, 2024). "PFKM deficiency is considered as a skeletal muscle glycogenosis, but the relative contribution of altered glucose metabolism in other tissues to the pathogenesis of the disease is not fully understood." (PMID 19696889, 2009). "Polyglucosan body disease (PBD) is a type of glycogen storage disease (GSD) and is mainly caused by mutations in eight different human genes, namely, GYG1, GBE1, RBCK1, PFKM, EPM2A, EPM2B (NHLRC1), PRDM8, and PRKAG2." (PMID 33413275, 2021). "Mutations in the gene for muscle phosphofructo-1-kinase (PFKM), a key regulatory enzyme of glycolysis, cause Type VII glycogen storage disease (GSDVII)." (PMID 19696889, 2009).
liver cancer (6 papers, 2021 to 2025). An epithelial or non-epithelial malignant neoplasm that arises from the liver. "Western blotting assessed the expression of ASIC1 and glycolysis-related enzymes, with siRNA transfections used to investigate ASIC1 and phosphofructokinase muscle-type (PFKM) in liver cancer cell survival." (PMID 40149892, 2025). "In conclusion, we have shown that the acidic tumor microenvironment enhances glycolysis and supports liver cancer cell survival by upregulating PFKM via the acid-sensing ion channel ASIC1." (PMID 40149892, 2025). "Our study reveals a link between ASIC1 and glycolytic metabolism in liver cancer, as PFKM expression was upregulated following ASIC1 overexpression." (PMID 40149892, 2025). "Our findings suggest that ASIC1 enhances liver cancer cell survival by upregulating PFKM-mediated glycolysis in an acidic tumor microenvironment." (PMID 40149892, 2025). "Taken together, our study shows that ASIC1 confers a survival advantage to liver cancer cells under acidic conditions by upregulating PFKM." (PMID 40149892, 2025). "We propose that targeting ASIC1 or PFKM could offer new therapeutic opportunities by depriving liver cancer cells of their metabolic adaptability to acidic environments." (PMID 40149892, 2025). "Notably, ZEB1 has been reported to upregulate PFKM, promoting glycolysis and thus advancing liver cancer progression and metastasis." (PMID 40149892, 2025). "This ASIC1/PFKM axis is pivotal for adapting liver cancer cells to metabolic stress." (PMID 40149892, 2025). "Finally, the expression of ZEB1 and PFKM were examined in human liver cancer specimens and non-tumorous liver tissues using immunohistochemical and Western blot." (PMID 33897890, 2021).
Obesity (5 papers, 2017 to 2025). Accumulation of substantial excess body fat. "Alongside transcriptional mitochondrial oxidative downregulation, we observed higher pyruvate levels in acquired obesity, accompanied by higher glycolytic phosphofructokinases (PFKM and PFKP) and LDHA protein levels." (PMID 33948567, 2021).
ovarian carcinoma (5 papers, 2020 to 2025). A malignant neoplasm originating from the surface ovarian epithelium. "The ovarian cancer patients with high expression of PFKM experienced significantly shorter overall survival." (PMID 33859186, 2021). "Here, we explored the role of PFKM S-nitrosylation modification induced by NOS1 on the metabolic switch in ovarian cancer." (PMID 33859186, 2021). "The expressions of both NOS1 and PFKM increase in different kinds of tumors and positively correlated with the progressive stages of ovarian cancer." (PMID 33859186, 2021). "PFKM expression was positively correlated with the progressive stages of ovarian cancer (GSE51373)." (PMID 33859186, 2021). "PFKM expression is positively correlated with the progressive stages of ovarian cancer." (PMID 33859186, 2021). "PFKM isoform was S-nitrosylated in our S-nitrosoproteome profile of ovarian cancer cells." (PMID 33859186, 2021). "Here we demonstrated that NOS1 induces PFKM S-nitrosation at Cys351 to stabilize tetramer of PFK1 and increase its activity, leading to the increase of the glycolysis in ovarian cancer cells." (PMID 33859186, 2021).
breast tumor (4 papers, 2017 to 2022). "Significant upregulation (p < 0.0001) of the glycolytic genes (HK2, PKM2, and PFKM) was observed in breast tumor tissues in comparison to their respective controls." (PMID 35328104, 2022). "Our results showed highly significant overexpression of the crucial glycolytic genes (i.e., HK2, PFKM, and PKM2) in breast tumors as compared to their adjacent controls." (PMID 35328104, 2022). "Hence, breast tumors with overexpression of HK2, PFKM, and PKM2 may potentially be more malignant due to enhanced aerobic glycolysis." (PMID 35328104, 2022).
glioma (4 papers, 2010 to 2026). A benign or malignant brain and spinal cord tumor that arises from glial cells (astrocytes, oligodendrocytes, ependymal cells). "Furthermore, our study also demonstrated that an increase in HK1, PFKM, and GAPDH expression could be associated with the CNS WHO grading of gliomas." (PMID 34573317, 2021). "The increased expression of HK2, PFKM, SLC2A1, and PKM2 induced by TGF-β has been observed in several types of cancer, including gliomas, particularly under hypoxic conditions." (PMID 40943648, 2025). "Due to this, we decided to analyze the expression levels of some glycolytic genes in pediatric glioma samples of different grades, and found that the HK1, PFKM, GAPDH, and LDHAL6A genes are overexpressed in human brain glioma biopsies." (PMID 34573317, 2021). "For this reason, the HK1, PFKM, and GAPDH genes could be essential for the progression of glioma to malignant grades, and in this way, they could be useful biomarkers and even targets for the therapy of gliomas." (PMID 34573317, 2021).
pancreatic cancer (4 papers, 2019 to 2025). "Studies have shown that pancreatic tumor cells exhibit low PFKM activity because of cellular O-GlcNAcylation, which leads to KRAS mutations." (PMID 35406597, 2022). "However, the mechanisms underlying the increased PFKM expression in pancreatic cancer has not been clearly demonstrated." (PMID 41184232, 2025).
prostate carcinoma (4 papers, 2019 to 2025). A carcinoma that arises from epithelial cells of the prostate gland. "Our work has highlighted GPI, PFKM, ALDOA, and PGK1 as key glycolysis-associated mRNAs that display CPSF1-dependent expression in prostate cancer cell lines." (PMID 39847481, 2025).
osteosarcoma (3 papers, 2024 to 2025). A usually aggressive malignant bone-forming mesenchymal neoplasm, predominantly affecting adolescents and young adults. "Altogether, we found ac4C driven RNA m6A modification can positively regulate the glycolysis of cancer cells and reveals a previously unrecognized signaling axis of NAT10/ac4C-YTHDC1/m6A-LDHA/PFKM in osteosarcoma." (PMID 38233839, 2024). "YTHDC1 recognizes differential m6A sites on PFKM and LDHA RNAs, which promotes osteosarcoma cell growth and regulates glycolysis pathway by increasing PFKM and LDHA mRNA stability in an m6A methylation-dependent manner." (PMID 38233839, 2024). "In this study, we demonstrate for the first time that ac4c driven RNA m6A modification can positively regulate the glycolysis of cancer cells and reveals a previously unrecognized signaling axis of NAT10/ac4C-YTHDC1/m6A-LDHA/PFKM in osteosarcoma." (PMID 38233839, 2024). "Together, these findings demonstrate a mechanism of ac4C driven RNA m6A modification and reveals a previously unrecognized signaling axis of NAT10-YTHDC1-LDHA/PFKM in osteosarcoma, shedding new light on the epigenetic regulation in human cancer." (PMID 38233839, 2024). "ac4C‐modified YTHDC1 mediates m6A methylation of PFKM and LDHA to regulate glucose metabolism and promote progression of osteosarcoma." (PMID 39640362, 2024). "Therefore, our findings suggest that NAT10 serves as an effective and novel therapeutic target for osteosarcoma through YTHDC1-mediated m6A modification, which can impact the translation efficiency of LDHA and PFKM." (PMID 38233839, 2024).
acute myocardial infarction (2 papers, 2021 to 2023). Necrosis of the myocardium, as a result of interruption of the blood supply to the area. "The purpose of this study is to explore the regulating role of microRNA-383-5p (miR-383-5p) in oxidative stress after acute myocardial infarction (AMI) through AMPK pathway via phosphofructokinase muscle-type (PFKM)." (PMID 34917202, 2021).
Insulin resistance (2 papers, 2020 to 2022). Increased resistance towards insulin, that is, diminished effectiveness of insulin in reducing blood glucose levels. "Paradoxically, expression quantitative trait loci studies (eQTLs) performed with the skeletal muscle of T2D subjects, found that PFKM gene expression was increased and associated with reduced glucose uptake and insulin resistance." (PMID 32977552, 2020). "Although heterozygous PFKM deficiency leads to insulin resistance, whether the decrease in buffering capacity within the muscle of humans with T2D could decrease PFKM enzyme activity and lead to onset of insulin resistance needs to be studied." (PMID 32977552, 2020).
maturity-onset diabetes (2 papers, 2003 to 2025). "Noteworthy, high PFKM expression activated the pathways such as taste transduction, maturity-onset diabetes of the young, neuroactive ligand-receptor interaction, and allograft rejection that might induce IPF." (PMID 40093327, 2025).
renal fibrosis (2 papers, 2024 to 2025). A final common manifestation of a wide variety of chronic kidney diseases characterized by glomerulosclerosis and tubulointerstitial fibrosis. "In another study, researchers discovered through miRNA sequencing analysis that MSC-EVs could ameliorate renal fibrosis by diminishing glycolysis in TECs mediated by miR-21a–5p targeting PFKM." (PMID 41194960, 2025).
Sepsis (2 papers, 2025 to 2026). Sepsis is defined as life-threatening organ dysfunction caused by a dysregulated host response to infection. "We previously demonstrated that the glycolytic enzyme 6-phosphofructokinase, muscle type (PFKM), modulates macrophage functions and its deficiency alleviates sepsis in mice." (PMID 41608568, 2026). "Nuclear accumulation of PFKM impaired phagocytosis through a non-glycolytic "moonlighting" function and exacerbated sepsis." (PMID 41608568, 2026).